ZNF726 (zinc finger protein 726)
Description:
May be involved in transcriptional regulation.
Synonyms: ZNF92P3
Tractability: PROTAC: ubiquitination databases record sites on it.
Gene: Protein-coding gene on chromosome 19 (23,914,876 to 23,945,159, forward strand). Ensembl gene ENSG00000213967.
Subcellular location: Nucleus
Pathways (Reactome):
Gene expression (Transcription): Generic Transcription Pathway
Gene Ontology:
Molecular function: DNA-binding transcription factor activity; RNA polymerase II cis-regulatory region sequence-specific DNA binding
Biological process: regulation of DNA-templated transcription; negative regulation of transcription by RNA polymerase II
Cellular component: nucleus
Genetic constraint (gnomAD): Loss-of-function variants: 12 observed, 9.65 expected, observed/expected ratio (o/e) 1.24, 90% interval 0.79 to 1.84. That is too few expected variants to judge how well the gene tolerates losing a copy. Missense variants: 864 observed, 686.84 expected, observed/expected ratio (o/e) 1.26, 90% interval 1.19 to 1.33. Synonymous variants: 287 observed, 229.21 expected, observed/expected ratio (o/e) 1.25, 90% interval 1.14 to 1.38.
Homologues: Orthologues: macaque ZNF726 (85% identical). Paralogues in human: ZNF254 (78% identical), ZNF728 (73% identical), ZNF724 (70% identical), ZNF429 (69% identical), ZNF681 (68% identical), ZNF676 (68% identical), ZNF93 (68% identical), ZNF708 (68% identical), ZNF43 (67% identical), ZNF85 (66% identical), ZNF493 (65% identical), ZNF90 (64% identical), and 164 more.
Diseases named in the same sentence as ZNF726 in open-access papers:
ZNF726 is named in the same sentence as 2 diseases in open-access papers, as found by Europe PMC text mining. Sharing a sentence is not in itself a finding about the gene and the disease. The quoted sentences say what the papers report.
tumor (2 papers, 2021). "Among other tumor cell lines, WNT2 and ZNF726 had the highest methylation in CRC, indicating that the role of WNT2 and ZNF726 genes in the CRC may be linked to methylation regulation." (PMID 34217303, 2021).
ZNF726 also shares sentences with these, for which no sentence is quoted: colon cancer (1 paper).